SCN1A (sodium voltage-gated channel alpha subunit 1)
Diseases named in the same sentence as SCN1A in open-access papers (continued):
Sharing a sentence is not in itself a finding about the gene and the disease.
Dravet syndrome (continued). "The present study assessed the anticonvulsant potential of the CBGA-related compounds, CBGA methyl ester and olivetolic acid, against hyperthermia-induced seizures in the Scn1a+/- mouse model of Dravet syndrome." (PMID 34980287, 2022). "A similar SpCas9-VP64 dual AAV vector system was used in two recent studies to activate the Kcn1 or the Scn1a gene to treat the respective mouse model for epilepsy or Dravet syndrome." (PMID 35152318, 2022). "Cannabigerolic acid (CBGA), a precursor cannabinoid in Cannabis sativa, has recently been found to have anticonvulsant properties in the Scn1a+/- mouse model of Dravet syndrome." (PMID 34980287, 2022). "Olivetolic acid displayed modest anticonvulsant activity against hyperthermia-induced seizures in the Scn1a+/- mouse model of Dravet syndrome despite poor brain penetration." (PMID 34980287, 2022). "In this study, we evaluated the anticonvulsant potential of Δ9-THCA in the Scn1a+/− mouse model of Dravet syndrome." (PMID 33998858, 2022). "In any case, Δ9-THCA is inferior to CBD as an anticonvulsant, with CBD displaying efficacy in the 6-Hz and MES seizure models, as well as the Scn1a+/− mouse model of Dravet syndrome." (PMID 33998858, 2022). "Next, we evaluated the efficacy of CBGA methyl ester and olivetolic acid against hyperthermia-induced seizures in Scn1a+/- mice, which models febrile seizures that occur in children with Dravet syndrome." (PMID 34980287, 2022). "We demonstrated that the genetic deletion of eEF2K in the Scn1a ± mice rescued the main phenotypes such as epileptic seizure and deficit in behavior, which characterized the Dravet syndrome suggesting eEF2K as a possible pharmacological target." (PMID 34980259, 2022). "In another study, neurons derived from two patients with Dravet syndrome demonstrated that genetic alterations of SCN1A differentially impacted electrophysiological impairment." (PMID 36552721, 2022). "In our cohort, SCN1A-related photosensitivity was Dravet syndrome, consistent with previous reports in the literature." (PMID 36034301, 2022). "CBGA has anticonvulsant effects against hyperthermia-induced seizures in the Scn1a+/- mouse model of Dravet syndrome." (PMID 34980287, 2022). "The majority of Dravet syndrome patients have a loss-of-function mutation in SCN1A, the gene that encodes the voltage-gated sodium channel Nav1.1." (PMID 34980287, 2022). "Some antiseizure medications that alleviate seizures in Dravet syndrome do not affect SCN1A, and some antiseizure medications that affect SCN1A aggravate seizures in Dravet syndrome." (PMID 36196775, 2022). "The manuscript presents a carefully examination of an intrinsic and synaptic electrophysiological characteristics in CA1 pyramidal cells in mice with Scn1a haploinsufficiency, an established mouse model of Dravet syndrome (DS)." (PMID 35523580, 2022). "In contrast, loss-of-function Scn1A mutations are associated with genetic epilepsy with febrile seizures plus (GEFS+) and Dravet syndrome, consistent with decreased activity of inhibitory GABAergic neurons." (PMID 35165201, 2022). "Motor deficits are common in Dravet syndrome: most of the patient are affected by ataxia, dysarthria, intention tremor and eye movement disorder and these features are replicated in Scn1a ± mice." (PMID 34980259, 2022). "Here, we use a Scn1a haploinsufficieny model of Dravet syndrome (DS) to investigate synaptic integration and input/output functions, which are fundamental forms of neuronal information processing." (PMID 35523580, 2022). "Genome editing is also being explored with CRISPR/Cas9-based gene therapy triggering SCN1A transcription in inhibitory neurons shown to ameliorate seizures in Dravet syndrome mice." (PMID 34690692, 2021).
Dravet syndrome (continued). "Studies in Scn1a−/− mouse models of Dravet syndrome have sought to identify neurological sequelae and symptoms of the defective Scn1a in mammals." (PMID 34445144, 2021). "The clinical diagnosis of Dravet syndrome is supported by the presence of abnormalities in the sodium channel gene SCN1A (found in 75% of cases)." (PMID 33924914, 2021). "This increase in poison exon inclusion alone resulted in a decrease of Scn1a mRNA to 50%, resulting in a reduced gene expression known to occur in Dravet syndrome." (PMID 33411776, 2021). "Dravet syndrome is a severe, infant-onset developmental and epileptic encephalopathy (DEE) with at least 80% of cases resulting from de novo pathogenic variants in SCN1A." (PMID 34086081, 2021). "Dravet syndrome, a genetic disorder which causes childhood epilepsy, occurs from mutations in the SCN1A gene encoding the Nav1.1 voltage-gated sodium channel." (PMID 34671313, 2021). "iPSC models of Dravet syndrome, along with animal models, have contributed to understanding the cell-intrinsic disease mechanisms of SCN1A dysfunction." (PMID 34713254, 2021). "Scn1a−/− animal models recapitulate some of the behavioral phenotypes observed in patients with Dravet syndrome." (PMID 34445144, 2021). "A CRISPR-Cas9 based strategy, which consists in positively and specifically modulating the expression of any gene of interest with a catalytically dead Cas9, has also been successfully used to promote Scn1a expression in mouse models of Dravet syndrome." (PMID 34671263, 2021). "These ASD genes included the Dravet syndrome gene SCN1A and the Timothy syndrome gene CACNA1C, but also GRIN2B, HTR2A, PCDH9, and other genes." (PMID 34188164, 2021). "While Dravet syndrome represent the main clinical phenotype for SCN1A-related disorders, milder clinical presentations are known that are typically seen in families." (PMID 33411776, 2021). "There is also strong phenotypic overlap with Dravet syndrome, a rare DEE most often caused by mutations in SCN1A." (PMID 33435571, 2021). "Dravet syndrome has a well-defined SCN1A genetic etiology and well-defined genotype-phenotype correlations in animal models." (PMID 34445144, 2021). "Scn1a+/− mice recapitulate features of Dravet syndrome, including spontaneous seizures, sudden death, and cognitive/behavioral deficits." (PMID 34086081, 2021). "Neuroactive steroids reduced spontaneous seizures and hyperthermia-induced seizures and prolonged survival in an Scn1a+/− mouse model of Dravet syndrome." (PMID 34445144, 2021). "A rAAV using a mouse dlx5/6 enhancer was also used in Scn1a mutant mice, a mouse model of Dravet Syndrome." (PMID 34671313, 2021). "In a review of Scn1a+/− mouse models of Dravet syndrome, it was noted that those bred on a 6N background were more susceptible to hyperthermia-induced seizures, yet had milder spontaneous seizures and improved survival rates relative to 6J crosses." (PMID 33910599, 2021). "In a model of Dravet syndrome, a 70% reduction in seizure frequency and severity was observed due to a 25% increase in Scn1a expression in the brain." (PMID 34853716, 2021). "De novo variants in genes that mediate synaptic transmission such as SCN1A and PCDH19 are often associated with Dravet syndrome." (PMID 34095830, 2021). "Encoded Therapeutics is currently preparing for clinical trials using ETX101 for SCN1A-positive Dravet syndrome patients." (PMID 34690692, 2021). "Ion channelopathies like α1-sodium channel subunit (SCN1A) and sodium-activated potassium channel gene (KCNT1), typically associated with Dravet syndrome and sleep-related hypermotor epilepsy, respectively, can co-occur with histologically proven FCD." (PMID 33551717, 2020). "This renders estimating an edema rate in the few Dravet syndrome/SCN1A sudden death cases unreliable." (PMID 32949224, 2020).
Dravet syndrome (continued). "Collectively, these results show that liraglutide reduces seizure susceptibility and cognitive dysfunction in the mouse model of Dravet syndrome, and exerts anti-apoptotic and neuroprotective effects in Scn1a KO mice and cells." (PMID 32184723, 2020). "Dravet syndrome (DS) is a severe developmental and epileptic encephalopathy (DEE) that is usually due to SCN1A genetic variants for the voltage-gated sodium channel Nav1.1." (PMID 33238377, 2020). "SICI is also reduced in SCN1A-related epilepsies such as Dravet syndrome (DS), which again reflects abnormal cortical inhibition networks, while the other TMS-derived markers of cortical excitability remain normal." (PMID 31736722, 2019). "The clinical presentation is coherent with Dravet syndrome (MIM 607208), usually caused by mutations involving SCN1A; however, the phenotypic variability in SCN1A mutation carriers is wide." (PMID 31694722, 2019). "By clinical exome sequencing, we identified two novel mutations: c.4973C>A (p.Thr1658Lys) in SCN1A gene and c.1283A>G (p.Tyr428Cys) in the SCN2A gene, whereas the third mutation c.3295G>T (p.Glu1099*) was already described in patients with Dravet syndrome." (PMID 31439038, 2019). "Strikingly, the seizure phenotypes and survival of Scn1a mutant mouse models of Dravet syndrome and GEFS+ can be dramatically improved by the co-expression of a heterozygous Scn8a loss-of-function allele." (PMID 29317669, 2018). "Dravet syndrome is closely related to the SCN1A gene, which was the most frequently-appearing gene showing variants in our study." (PMID 30185235, 2018). "In this study, we demonstrated the antiepileptic effect of GS967 in the Scn1a+/− mouse model of Dravet syndrome, an unexpected result given that GS967 is a sodium channel blocker." (PMID 28490751, 2017). "Mice with heterozygous deletion of Scn1a (Scn1a+/−) recapitulate many features of Dravet syndrome, including spontaneous seizures, hyperthermia-induced seizures and premature death." (PMID 28490751, 2017). "Scn1a+/− mice recapitulate many features of Dravet syndrome, including spontaneous seizures, premature death and seizures induced by hyperthermia." (PMID 29127345, 2017). "Premature mortality in Dravet syndrome can be modeled in Scn1a+/− mice on a [C57BL/6 J x 129S6/SvEvTac]F1 genetic background." (PMID 28490751, 2017). "We describe a distinct SCN1A phenotype, early infantile SCN1A encephalopathy, which is readily distinguishable from the well-recognized entities of Dravet syndrome and genetic epilepsy with febrile seizures plus." (PMID 28794249, 2017). "For example, upregulating Scn1a expression using anti-sense RNA approaches has been shown to be an effective means of reducing seizures in a model of Dravet syndrome." (PMID 29069078, 2017). "Similar to individuals with Dravet syndrome, seizures can be provoked in Scn1a+/− mice by elevated body temperature." (PMID 29127345, 2017). "Dravet syndrome is caused by a loss-of-function mutation in SCN1A, which encodes for the Nav1.1 channel, located in inhibitory neurons." (PMID 26252990, 2016). "Both Dravet syndrome patients and F1.Scn1a+/- Dravet mice experience seizures triggered by hyperthermia." (PMID 27768696, 2016). "Heterozygous deletion of mouse Scn1a models features of Dravet syndrome, including spontaneous seizures, thermal seizure sensitivity, cognitive deficits, and increased mortality." (PMID 27768696, 2016). "To answer this question, we focused our study on screenings of the SCN1A gene (OMIM: #152389) in Dravet syndrome (DS), one of the genetically most homogeneous epilepsy syndromes." (PMID 27465585, 2016).
Dravet syndrome (continued). "SCN1A mutations with increased persistent current were observed in patients with generalized epilepsy with febrile seizures plus (GEFS+) and Dravet Syndrome." (PMID 26029160, 2015). "All patients who met the clinical diagnosis criteria for Dravet Syndrome had SCN1A gene sequencing performed." (PMID 26933548, 2015). "Together, this resulted in a similar proportion of established SCN1A-related Dravet syndrome as in our study." (PMID 23762420, 2013). "Both short or prolonged, generalized or unilateral, and febrile or afebrile vaccination-related seizures occurred in children with SCN1A-related Dravet syndrome." (PMID 23762420, 2013). "The seizure had occurred within 24 h (median 7.5 h) after administration of DT(P)-IPV(-)Hib vaccines in the majority of children diagnosed with SCN1A-related Dravet syndrome." (PMID 23762420, 2013). "All children with SCN1A-related Dravet syndrome had developed multiple seizure types that were temperature-sensitive." (PMID 23762420, 2013). "Our genetic testing showed that 1 of 3 (33.3%) patients with clinical Dravet syndrome and 3 of 20 (15%) patients that diagnosed as GEFS+, had SCN1A mutation." (PMID 24665294, 2013). "In total, 15 children (1.2% of the total cohort (n = 1269), 95%-confidence interval (CI):0.6 to1.8%) were diagnosed with SCN1A-related Dravet syndrome." (PMID 23762420, 2013). "Our study shows that although SCN1A-related Dravet syndrome is a rare disorder, 2.5% of reported seizures following vaccinations in the first year of life occurred in children with this disorder." (PMID 23762420, 2013). "Our genetic testing showed that 1 of 3 (33.3%) patients with clinically Dravet syndrome and 3 of 20 (15%) patients diagnosed as GEFS+, had SCN1A mutation." (PMID 24665294, 2013). "2.5% (n = 18; 95%CI:1.2 to 3.4%) of all reported seizures in the first year of life had occurred in children with SCN1A-related Dravet syndrome." (PMID 23762420, 2013). "Seizures in children with SCN1A-related Dravet syndrome were classified as afebrile (45.0%), simple febrile (20.0%), complex febrile (15.0%) or atypical seizures (20.0%)." (PMID 23762420, 2013). "This study was designed to provide guidance for physicians, pediatrics, and pediatric neurologists to diagnose the patients with Dravet syndrome or GEFS+ and to provide appropriate indications for mutation analysis of the SCN1A gene." (PMID 24665294, 2013). "We generated iPSCs from a Dravet syndrome patient with a c.4933C>T substitution in SCN1A, which is predicted to result in truncation in the fourth homologous domain of the protein (p.R1645*)." (PMID 23639079, 2013). "Only two seizures in children with SCN1A-related Dravet syndrome occurred after vaccinations in the second year of life, representing 0.3% (95%CI:0.0 to 0.8%) of reported seizures in the second year of life." (PMID 23762420, 2013). "Among seizures reported after the second or third DTP-IPV(-)Hib vaccination, the proportion of SCN1A-related Dravet syndrome was the highest." (PMID 23762420, 2013). "Of all reported seizures following vaccinations in the first year of life, 2.5% (95%CI:1.3 to 3.6%) were due to SCN1A-related Dravet syndrome, as were 5.9% of reported seizures (95%CI:3.1 to 8.7%) after 2nd or 3rd DTP-IPV-Hib vaccination." (PMID 23762420, 2013). "Within this cohort, children with possible Dravet syndrome were followed up, to estimate the prevalence of SCN1A-related Dravet syndrome and describe the clinical characteristics of seizures following vaccinations." (PMID 23762420, 2013). "Children diagnosed with SCN1A-related Dravet syndrome had a younger age at first seizure following vaccination, and more often had second and third seizures reported after subsequent vaccinations than other children." (PMID 23762420, 2013). "Only in part of all children with clinical characteristics of Dravet syndrome, SCN1A-analysis was performed." (PMID 23762420, 2013).
Dravet syndrome (continued). "We have previously reported that the similarity between PCDH19 and SCN1A clinical spectra comprises Dravet syndrome; now, we show that it also extends to that of GEFS+." (PMID 21053371, 2011). "The multifactorial etiology of Dravet syndrome proposed by many investigators suggests that it is very likely that genes responsible for Dravet syndrome will far outnumber SCN1A and SCN9A." (PMID 19763161, 2009). "Of the 9 Dravet syndrome patients with SCN9A variants, six harbor either splice site or missense mutations in SCN1A." (PMID 19763161, 2009). "Conversely, in SCN1A-related epilepsies such as Dravet syndrome, vigabatrin’s effects are variable." (PMID 41614796, 2025). "Mouse models of heterozygous Scn1a knockout can reproduce Dravet syndrome in one mouse strain but cause no overt phenotype in a different mouse strain." (PMID 40047626, 2025). "Approximately 70–80% of Dravet syndrome cases are associated with variants in the SCN1A gene, with more than 90% being de novo and not inherited from parents." (PMID 40903466, 2025). "Additionally, pharmacological agents such as fenfluramine, stiripentol, and cannabidiol, although not acting directly on sodium channels, represent recognized therapeutic options for SCN1A-related Dravet syndrome." (PMID 41515912, 2025). "A notable example is the application of ASO therapy in a mouse model of SCN1A-associated Dravet syndrome, where blocking a non-productive splicing event increased SCN1A-mRNA and NaV1.1 protein levels, ultimately reducing seizure frequency." (PMID 40687881, 2025). "The hippocampal formation acts as an epicenter of more intense structural changes even in epilepsy syndromes in which no clear indication of seizure genesis in the hippocampus exists, such as SCN1A-related Dravet syndrome and idiopathic generalized epilepsy syndromes." (PMID 38238304, 2024). "Our data show that maintenance of physiological levels of Nav1.1 during brain development is not sufficient to prevent Dravet symptoms and that long-lasting restoration of Scn1a gene expression would be required to grant optimal clinical benefit in patients with Dravet syndrome." (PMID 37812819, 2024). "Lastly, in an Scn1a+/− mouse model of Dravet syndrome, PV neurons are transiently hypoexcitable during development, whereas later they show an increased firing rate, both interictally and at seizure onset, and a decrease in synchrony in the transition to seizure." (PMID 39392867, 2024). "Variable expressivity is common among individuals with Dravet syndrome due to SCN1A haploinsufficiency, supporting that genetic modifiers may contribute to clinical severity." (PMID 38862622, 2024). "Moreover, administering GS967 -a selective blocker of Nav1.6- reduces spontaneous seizures and prolongs the survival of heterozygous mice of N1768D Scn8a and Scn1a+/− Dravet syndrome." (PMID 39513870, 2024). "In contrast to the ameliorating effect of Cacna1g on the mouse model of Dravet syndrome, CACNA1A has a worsening effect on Dravet syndrome, meaning subjects carrying both SCN1A and CACNA1A variants develop absence seizures earlier and more frequently than patients with only SCN1A mutations." (PMID 39513870, 2024). "Genetic testing was recommended which revealed the SCN1A gene consistent with Dravet syndrome." (PMID 38983583, 2024). "Several studies have shown that Dravet syndrome model mice: Scn1a KO mice have a high number of apoptotic neurons following seizures, but the precise mechanism underlying this remains unclear." (PMID 38674042, 2024). "Similarly, the lethal seizure shows incomplete penetrance in the mouse models of Dravet syndrome, with 50% of Scn1a+/− mice remaining unaffected." (PMID 39513870, 2024). "Dravet syndrome is caused by mutations in SCN1A, the gene that encodes Nav1.1." (PMID 37374132, 2023).